MED12 (mediator complex subunit 12)
Diseases named in the same sentence as MED12 in open-access papers (continued):
Sharing a sentence is not in itself a finding about the gene and the disease.
X-linked intellectual disability (5 papers, 2016 to 2023). An X-linked intellectual deficiency in which not enough information is known, reported or published to indicate whether a gene causes non-syndromic or syndromic presentations. "Mutations in MED12 cause X-linked intellectual disability and other anomalies collectively grouped as MED12-related disorders." (PMID 32174975, 2020). "The RNA polymerase II transcriptional Mediator subunit Med12 is broadly implicated in vertebrate brain development, and genetic variation in human MED12 is associated with X-linked intellectual disability and neuropsychiatric disorders." (PMID 27188461, 2016). "Interestingly, point mutations in human OGT and MED12, another Mediator component, co-segregate in individuals affected with X-linked intellectual disability (XLID)." (PMID 29588363, 2018). "Mutations in MED12 at Xq13 causing X-linked intellectual disability (XLID) called MED12-related disorders, which include four phenotypes: FGS1, LS, OSMKB, and NSID." (PMID 32174975, 2020). "Moreover, germline variants of MED12 and MED12L also contain large IDR domains, and are found in several genetic disorders associated with X-linked intellectual disability, neuronal and developmental disorders, failure of hematopoietic-specific transcriptional programs, and cancer." (PMID 34683473, 2021).
X-linked Ohdo syndrome (5 papers, 2018 to 2025). "Germline mutations in the MED12 gene have been associated with Opitz–Kaveggia syndrome, also known as FG syndrome 1 (OMIM#305450), Lujan–Fryns syndrome (OMIM#309520), which overlaps with FG syndrome 1, and X-linked Ohdo syndrome (OMIM#300895)." (PMID 31906484, 2020).
lung carcinoma (4 papers, 2016 to 2023). "Other MED genes such as MED8 were found to associate with renal cell carcinoma, while MED12 associates with lung cancer." (PMID 37511575, 2023). "AXL activation and MED12 loss induced an EMT-like phenotype, which is associated with EGFR-TKI resistance in lung cancer." (PMID 29930762, 2018). "In lung cancer, MED12 was transcriptionally overexpressed in 36% (n = 226/628) and underexpressed in 21% (n = 132/628) of the samples." (PMID 27050271, 2016). "Differential expression of MED8 in renal cell carcinoma (RCC) and MED12 in lung cancer (LCa) were validated and further investigated by immunohistochemical staining on tissue microarrays containing large numbers of specimen." (PMID 27050271, 2016). "MED12 in LCa was chosen, because this Mediator complex subunit is frequently altered in diverse cancer entities and was not yet investigated on a large lung cancer cohort with detailed clinical information." (PMID 27050271, 2016).
non-small cell lung carcinoma (4 papers, 2017 to 2025). A group of at least three distinct histological types of lung cancer, including non-small cell squamous cell carcinoma, adenocarcinoma, and large cell carcinoma. "Non-small cell lung cancer (NSCLC) as the leading cause of cancer- related death all over the world, the relevance of MED12 in which including mutations, expression and function has not been explored." (PMID 31072327, 2019).
ovarian carcinoma (4 papers, 2012 to 2026). A malignant neoplasm originating from the surface ovarian epithelium. "To elucidate whether MED12 is involved in the tumorigenesis of other oestrogen- and progesterone-dependent tumours, we screened breast and ovarian cancer samples representing different histological subtypes for MED12 exon 2 mutations." (PMID 23132392, 2012). "Together, we deduced that MED12, LRP2, PIK3R2, CCNE1, and LRP1B might be potential biomarkers for immunotherapy of ovarian cancer." (PMID 33432021, 2021).
pancreatic cancer (4 papers, 2015 to 2025). "Interestingly, L1 RNA expression in pancreatic cancer has been linked to loss of MED12 gene and MED12 gain-of-function hotspot mutations are driver mutations in ~ 70% of ULs." (PMID 40264183, 2025). "MED12, also a subunit of the kinase, was highly overexpressed in lung (36%, n = 226/628) and pancreatic cancer (100%, n = 10/10)." (PMID 27050271, 2016).
phyllodes tumors of the breast (4 papers, 2015 to 2025). "Phyllodes tumors of the breast, as a group, displayed a significantly higher frequency of mutations affecting MED12 (59% vs 5%, Fisher's exact test, P = 0.0002) and the promoter of TERT (45% vs 0, Fisher's exact test, P = 0.0006) than adenosarcomas." (PMID 28267263, 2017). "Additionally, genetic analysis of MED12, a gene frequently associated with phyllodes tumors of the breast, was performed, and no pathogenic mutations were detected." (PMID 41488090, 2025).
sarcoma (4 papers, 2012 to 2023). A usually aggressive malignant neoplasm of the soft tissue or bone. "PRDM10 gene fusions with either MED12 or CITED2 have been reported in a small proportion of undifferentiated pleomorphic sarcomas." (PMID 36440963, 2023). "Among the studied tumors, there were five uterine LMS and the authors observed no MED12 mutation in these samples as in other sarcomas." (PMID 22768200, 2012).
schizophrenia (4 papers, 2013 to 2018). A major psychotic disorder characterized by abnormalities in the perception or expression of reality. "Genetic variation in MED12 which has been implicated in neural development is associated with schizophrenia, and its mutations link with deregulated GLI3-dependent sonic hedgehog signaling pathway." (PMID 25522158, 2014).
autism (3 papers, 2013 to 2023). Persistent deficits in social interaction and communication and interaction as well as a markedly restricted repertoire of activity and interest as well as repetitive patterns of behavior. "Recently, a patient with severe ID and autism was found to be affected by FXS while also carrying a pathogenic variant in MED12 (MEDiator complex subunit 12), an X-linked gene located in Xq13.1." (PMID 34946857, 2021). "MED12 is linked to the sonic hedgehog pathway and mutations in the gene are associated with mental retardation and autism like features." (PMID 24007566, 2013). "For example, the autism-associated MED12 gene showed a unique PIE-FMR1 target site in the CDS." (PMID 37280234, 2023).
congenital heart disease (3 papers, 2020 to 2023). A heart disease that is present at birth. "In the oldest patient in this study, the postnatal findings of hallux rigidus and congenital heart disease (CHD) prompt a diagnosis of MED12 deficiency, although the patient failed to receive a comprehensive genetic test." (PMID 37501721, 2023). "This novel variant is a likely pathogenic variant of uncertain significance and it could broaden the spectrum of genes involved in the development of congenital heart diseases and the phenotypic range of MED12-related disorders." (PMID 32682435, 2020).
leiomyomatosis (3 papers, 2015 to 2023). A condition characterized by the presence of numerous small benign smooth muscle neoplasms located throughout the body. "MED12 codes for a key transcriptional regulator of RNA polymerase 2, and mutations of this gene lead to a highly penetrant hereditary form of leiomyomatosis." (PMID 37628676, 2023).
leukemia (3 papers, 2012 to 2021). A malignant (clonal) hematologic disorder, involving hematopoietic stem cells and characterized by the presence of primitive or atypical myeloid or lymphoid cells in the bone marrow and the blood. "U2AF1 p.R35L was shown to induce aberrant splicing of downstream target genes, and shRNA knockdown of MED12 and USP9X was shown to confer resistance to apoptosis following T-ALL relevant chemotherapy drug treatment in Jurkat leukemia cells." (PMID 27602765, 2016).
mesenchymal tumors (3 papers, 2012 to 2024). "Altogether 155 malignant mesenchymal tumours were analysed for MED12 exon 2 mutations." (PMID 23132392, 2012). "These include both benign and malignant mesenchymal tumours, oestrogen- and progesterone-dependent tumours, and haematological malignancies, as retroviral insertions in Med12 have been reported to participate in the development of leukaemias in murines." (PMID 23132392, 2012).
myoma (3 papers, 2016 to 2025). "MED12 mutations could either be the only genetic aberration detected in a myoma or coexist with other “driver” mutations (HMGA2, FH, COL4A5-COL4A6)." (PMID 36982825, 2023). "Driver mutations in MED12, HMGA2 and other genes appear to be emerging in undifferentiated cells at the early stages of UL tumorigenesis and largely define the fate of each myoma." (PMID 36982825, 2023).
Obesity (3 papers, 2021 to 2025). Accumulation of substantial excess body fat. "The pathogenesis of fibroids is multifactorial, involving hormonal dysregulation (particularly estrogen and progesterone), MED12 gene mutations, extracellular matrix accumulation, and modifiable risk factors such as vitamin D deficiency and obesity." (PMID 41585879, 2025). "Intriguingly, oxidative stress associated with obesity may preferentially mutate MED12 via NOX4 and TGF-β3-dependent pathways." (PMID 37628676, 2023). "The current study findings implicate MED12 (although not exclusively this gene, as others may also be implicated) as potentially important in obesity-mediated fibroid genesis via a ROS–DNA damage pathway." (PMID 37628676, 2023). "Knockdown of cardiac MED12 and MED13 in Drosophila increases fat accumulation and induces obesity, which suggests that like MED13, cardiac MED12 also can control metabolism homeostasis." (PMID 33390853, 2021). "MED12 and MED13 have similar functions in controlling obesity in Drosophila, especially heart and muscle MED12 and MED13." (PMID 33390853, 2021).
uterine tumor (3 papers, 2012 to 2019). "We thus assessed the β-catenin expression profile by immunohistochemistry in this uterine tumor series in order to see if the Wnt/β-catenin pathway was activated in these tumors, and if MED12 alterations were associated with a peculiar β-catenin pattern." (PMID 22768200, 2012). "Summary of MED12 mutations observed in the series of 33 uterine tumors." (PMID 22768200, 2012). "However, collectively these results show that MED12 may be implicated in the early steps of both benign and malignant uterine tumor development, its expression being inhibited in a subset of tumors, those with malignant potential." (PMID 22768200, 2012). "As a result, even if MED12 mutations are not restricted to tumors without genomic alterations, it seems that inhibition of its expression is specific to malignant rearranged uterine tumors." (PMID 22768200, 2012). "MED12 expression loss may contribute to the oncogenesis process of this subset of uterine tumors but not to LMS from other locations, meaning that these tumors could be two different entities or at least originating from distinct genetics and/or cell types." (PMID 22768200, 2012). "The same authors concluded that the Wnt/β-catenin pathway does not seem constitutively activated in MED12 mutated tumors, and they hypothesize that if MED12 mutations play a role in uterine tumor development, it is probably not through Wnt target genes activation in association with β-catenin." (PMID 24163697, 2013). "The Wnt/β-catenin pathway does not seem constitutively activated in these mutated tumors and we could thus hypothesize that if MED12 mutations play a role in uterine tumor development it's probably not through Wnt target genes activation in association with β-catenin." (PMID 22768200, 2012). "In the same manner, it could be of great interest to study non-uterine LM to see if MED12 alterations are really exclusive to uterine tumors." (PMID 22768200, 2012).
acute lymphoblastic leukemia (2 papers, 2012 to 2021). Leukemia with an acute onset, characterized by the presence of lymphoblasts in the bone marrow and the peripheral blood. "Other rearrangement partners of HOXA9 have been reported in lymphoid malignancies, such as TRB in T cell acute lymphoblastic leukemia (T-ALL) patients and MED12 in a pediatric patient with B cell acute lymphoblastic leukemia (B-ALL)." (PMID 34367969, 2021).
acute myeloid leukaemia (2 papers, 2012 to 2018). "However, a study of acute myeloid leukemia cells found that silencing of MED12 is associated with transcriptional repression." (PMID 29530929, 2018).
adrenocortical carcinoma (2 papers, 2015 to 2019). "Whereas MED12 mutations in other positions have been identified in prostate and adrenocortical carcinomas in much lower frequency (5%) 8,9, MED12 exon 2 mutations in other tumors have been rare events." (PMID 25865354, 2015).
Alpha-thalassemia (2 papers, 2016 to 2024). Alpha-thalassemia is an inherited hemoglobinopathy characterized by impaired synthesis of alpha-globin chains leading to a variable clinical picture depending on the number of affected alleles.
behavioral disorder (2 papers, 2018 to 2020). "MED12 gene, mapped to Xq13.1, is known to show germline mutations all across its 45 exons in different clinical phenotypes like, neurodevelopmental and behavioral disorders." (PMID 30619444, 2018).
colorectal tumours (2 papers, 2012 to 2017). "Although these mutations may have occurred just by chance, these findings suggest that specific MED12 exon 2 mutations may also be involved, albeit rarely, in the development of colorectal tumours." (PMID 23132392, 2012). "Subunit Med12 interacts with β‐catenin, and it has been identified as an important transducer of Wnt/β‐catenin signalling in the development of colorectal tumours." (PMID 28631286, 2017).
developmental delay (2 papers, 2013 to 2025). "We identified a heterozygous missense variant in MED12 c.3412 C > T; p.Arg1138Trp on the X chromosome, as a de novo variant in a four-year-old female (Patient 1) with multiple congenital anomalies and developmental delay." (PMID 41023835, 2025). "We investigate a MED12 c.3412 C > T, p.Arg1138Trp variant located on the X chromosome, identified in seven female individuals with severe congenital abnormalities and developmental delays." (PMID 41023835, 2025). "A novel X-linked disorder with developmental delay and autistic features with duplication of Xq12-q13.3 involves the MED12 gene." (PMID 24007566, 2013).
dilated cardiomyopathy (2 papers, 2022 to 2023). Cardiomyopathy which is characterized by dilation and contractile dysfunction of the left and right ventricles. "It was reported that 1 of the components of the Mediator complex, MED12, regulates postnatal heart function and deletion of MED12 causes progressive dilated cardiomyopathy." (PMID 35167494, 2022).
gastric cancer (2 papers, 2021 to 2024). A primary or metastatic malignant neoplasm involving the stomach. "The downregulation of MED12 might explain why EGFR Inhibitor therapy was ineffective in previous clinical trials for advanced gastric cancer." (PMID 38467827, 2024).
lung adenocarcinoma (2 papers, 2016 to 2019). A carcinoma that arises from the lung and is characterized by the presence of malignant glandular epithelial cells. "To determine the biological role of MED12 in NSCLC, we knocked out endogenous MED12 in human lung adenocarcinoma cells PC9 and SPC-A1 using the CRISPR-Cas9 system and reconstitution of exogenous MED12 using Lentiviral system." (PMID 31072327, 2019). "Both, lung adenocarcinoma (AC) and squamous cell carcinoma (SCC) exhibited a significantly elevated MED12 nuclear protein expression as compared to benign tissue (p < 0.001)." (PMID 27050271, 2016).
Macrocephaly (2 papers, 2025). Occipitofrontal (head) circumference greater than 97th centile compared to appropriate, age matched, sex-matched normal standards. "MED12 variants are typically associated with X-linked syndromes featuring macrocephaly (Lujan-Fryns and Opitz-Kaveggia syndromes)." (PMID 40019509, 2025).
malignant phyllodes tumor (2 papers, 2016 to 2024). A phyllodes tumor with sarcomatous stroma. "Recent gene sequencing studies revealed the presence of variety of mutations in malignant phyllodes tumors of which MED12 [Mediator Complex Subunit 12] mutation appears to be the most consistent and shared by both malignant and benign fibroepithelial tumors." (PMID 26625196, 2016).
microcephaly (2 papers, 2018 to 2025). A congenital or acquired developmental disorder in which the circumference of the head is smaller than normal for the person's age and sex. "Case UniPD_0210 with the p.(Ala1383Thr) variant in MED12 also presented microcephaly." (PMID 40019509, 2025). "Conversely, three cases with pathogenic variants in CHD8, WAC, and MED12 exhibited microcephaly, despite these genes typically not being associated with reduced head size." (PMID 40019509, 2025). "In addition to the MED12 subunit, a disruption of CDK19 was reported in a patient with ID, microcephaly and congenital retinal folds." (PMID 29740699, 2018).
parathyroid adenoma (2 papers, 2019 to 2024). "Among those genes up-regulated in parathyroid adenomas, some, such as MED12, KMT5A, BMP2K, and ATAD2, are implicated in cell proliferation and transcriptional regulation, supporting the notion that they potentially contribute to tumorigenesis." (PMID 30832348, 2019). "The expression of MED12 is reported to be altered in parathyroid gland adenomas in previous studies with mass spectrometry." (PMID 39064529, 2024). "The overall rate of positive immunohistochemical staining for MED12 is 66%, demonstrating a positive reaction in the sporadic parathyroid adenoma." (PMID 39064529, 2024). "Materials and Methods: Fifty-one parathyroid adenomas were analyzed for ANXA2, MED12, MAPK1 and VDR expressions." (PMID 39064529, 2024). "ANXA2, MED12, MAPK1 and VDR proved to have a positive staining in the immunohistochemical study of sporadic parathyroid adenomas in varying intensity and allocation percentages." (PMID 39064529, 2024). "Immunohistochemical analysis of ANXA2, MED12, MAPK1 and VDR proteins in sporadic parathyroid adenoma confirmed their expression in parathyroid cells." (PMID 39064529, 2024). "The aim of our study is to evaluate the quantitative expression of four gene proteins (ANXA2, MED12, MAPK1 and VDR) by immunohistochemical analysis in tissue samples of parathyroid adenoma, as well as their qualitative characteristics." (PMID 39064529, 2024). "The aim of this study is to evaluate the immunohistochemical staining of ANXA2, MED12, MAPK1 and VDR in parathyroid adenoma tissue." (PMID 39064529, 2024).